CDH5 (cadherin 5)
Description:
Cadherins are calcium-dependent cell adhesion proteins (By similarity). They preferentially interact with themselves in a homophilic manner in connecting cells; cadherins may thus contribute to the sorting of heterogeneous cell types. This cadherin may play a important role in endothelial cell biology through control of the cohesion and organization of the intercellular junctions (By similarity). It associates with alpha-catenin forming a link to the cytoskeleton. Plays a role in coupling actin fibers to cell junctions in endothelial cells, via acting as a cell junctional complex anchor for AMOTL2 and MAGI1 (By similarity). Acts in concert with KRIT1 and PALS1 to establish and maintain correct endothelial cell polarity and vascular lumen (By similarity). These effects are mediated by recruitment and activation of the Par polarity complex and RAP1B. Positively regulates reorientation of actin stress fibers and endothelial cell reorientation in response to cellular mechantransduction. Required for activation of PRKCZ and for the localization of phosphorylated PRKCZ, PARD3, TIAM1 and RAP1B to the cell junction. Associates with CTNND1/p120-catenin to control CADH5 endocytosis (By similarity).
Synonyms: CD144; 7B4
Tractability: Antibody: UniProt places it where antibodies can reach, with high confidence; its Gene Ontology location is reachable by antibodies, with high confidence; UniProt predicts a signal peptide or a membrane-spanning region; the Human Protein Atlas places it where antibodies can reach.
Gene: Protein-coding gene on chromosome 16 (66,366,636 to 66,404,784, forward strand). Ensembl gene ENSG00000179776.
Subcellular location: Cell junction, adherens junction; Cell membrane; Cytoplasm
Subcellular location (Human Protein Atlas): Plasma membrane; Nuclear membrane; Nucleoplasm
Pathways (Reactome):
Cell-Cell communication: Adherens junctions interactions
Cellular responses to stimuli: High laminar flow shear stress activates signaling by PIEZO1 and PECAM1:CDH5:KDR in endothelial cells
Signal Transduction: VEGFR2 mediated vascular permeability
Gene Ontology:
Molecular function: beta-catenin binding; BMP receptor binding; fibrinogen binding; protein binding; protein phosphatase binding; protein tyrosine kinase binding; signaling receptor binding; signaling receptor complex adaptor activity; transmembrane transporter binding; vascular endothelial growth factor receptor 2 binding; cadherin binding; cell-cell adhesion mediator activity; calcium ion binding
Biological process: adherens junction organization; bicellular tight junction assembly; blood vessel endothelial cell migration; cell surface receptor signaling pathway; cell-cell adhesion; cell-cell adhesion mediated by cadherin; cell-cell junction assembly; intracellular calcium ion homeostasis; negative regulation of endothelial cell apoptotic process; negative regulation of inflammatory response; negative regulation of microtubule polymerization; positive regulation of angiogenesis; positive regulation of BMP signaling pathway; positive regulation of cell migration; positive regulation of establishment of endothelial barrier; positive regulation of gene expression; positive regulation of intracellular signal transduction; positive regulation of protein-containing complex assembly; protein localization to bicellular tight junction; regulation of establishment of cell polarity; regulation of vascular permeability; transforming growth factor beta receptor signaling pathway; calcium-dependent cell-cell adhesion; cell migration; cell migration involved in sprouting angiogenesis; and 5 more
Cellular component: adherens junction; cell surface; cell-cell junction; plasma membrane; bicellular tight junction; catenin complex; cell junction; cytoplasm; membrane; cell periphery; external side of plasma membrane
Genetic constraint (gnomAD): Loss-of-function variants: 30 observed, 61.57 expected, observed/expected ratio (o/e) 0.49, 90% interval 0.36 to 0.66. The upper end of that interval is the gene's LOEUF score, 0.66, which puts it in group 2 of 6, group 1 being the genes least tolerant of losing a copy. Missense variants: 877 observed, 1,027.5 expected, observed/expected ratio (o/e) 0.85, 90% interval 0.81 to 0.9. Synonymous variants: 434 observed, 433.85 expected, observed/expected ratio (o/e) 1, 90% interval 0.92 to 1.08.
Homologues: Orthologues: chimpanzee CDH5 (99% identical), macaque CDH5 (98% identical), rabbit CDH5 (82% identical), pig CDH5 (79% identical), dog CDH5 (79% identical), rat Cdh5 (76% identical), mouse Cdh5 (75% identical), guinea pig CDH5 (70% identical), tropical clawed frog cdh5 (53% identical). Paralogues in human: CDH20 (40% identical), CDH11 (40% identical), CDH18 (40% identical), CDH10 (39% identical), CDH7 (39% identical), CDH6 (39% identical), CDH9 (39% identical), CDH8 (39% identical), CDH24 (38% identical), CDH12 (38% identical), CDH22 (37% identical), CDH19 (35% identical), and 21 more.
Diseases named in the same sentence as CDH5 in open-access papers:
CDH5 is named in the same sentence as 292 diseases in open-access papers, as found by Europe PMC text mining. Sharing a sentence is not in itself a finding about the gene and the disease. The quoted sentences say what the papers report.
melanoma (97 papers, 2006 to 2025). A malignant, usually aggressive tumor composed of atypical, neoplastic melanocytes. "High expression of CDH5 acts as unfavorable prognostic indicator in melanoma and breast cancer, while CDH6 expression is associated with poor outcome in renal and ovarian cancer." (PMID 41039222, 2025). "In melanoma, CDH5 expression was associated with the activation of the Notch pathway." (PMID 39172098, 2024). "CDH5 has been reported to be associated with breast cancer metastasis and aggressive melanoma." (PMID 27362942, 2016). "CDH5 exhibits a broader overexpression profile in cancer, being commonly observed in metastatic breast cancer, lung cancer, melanomas, gastric cancer, and pancreatic neuroendocrine tumors." (PMID 41039222, 2025). "The efficacy was demonstrated using either colorectal cancer cells expressing CDH17 or CDH5-expressing melanoma cells, owing to the high homology of the RGD flanking sequences." (PMID 41039222, 2025). "In the midnight blue module, the hub Flt1 (fms-related tyrosine kinase 1) is a VEGF receptor that participates in the proliferation of melanoma cells, whereas Cdh5 (VE-cadherin) is highly expressed in metastatic melanoma." (PMID 32831131, 2020). "Cdh5-CreERRosaYFP mice were inoculated with B16-F0 melanoma cells at D0 and injected with a single dose of tamoxifen on D3." (PMID 30604758, 2019). "Regarding vasculogenic mimicry, CDH5 regulates EPH Receptor A2 (EphA2) expression in melanoma cells and, conversely, CDH5 expression was significantly decreased after knockdown of hypoxia-inducible factors (HIF1α or HIF2α) in glioblastoma." (PMID 31324051, 2019). "Furthermore, the induction of endothelial CDH5 in melanoma spheres revealed an unexpected link between melanoma stemness features and its putative endothelial-like phenotypic properties, supporting the results obtained with our tumor models." (PMID 32230715, 2020). "Importantly, we detected a significant induction of both ADAMTS1 and CDH5, implying again a role for these molecules in melanoma plasticity." (PMID 32230715, 2020). "In addition, we reported the interaction of CDH5 with α2β1 integrin in melanoma and breast cancer cells to activate the integrin signaling pathway, promoting migration and invasion and, consequently, metastasis in a similar way to CDH17." (PMID 31324051, 2019). "Note the presence of EPHA2 that was regulated by CDH5 for vasculogenic mimicry in melanoma cells." (PMID 31324051, 2019). "Intriguingly, in melanoma cell lines this gene enhances invasiveness and proliferation, surprisingly limiting vasculogenic mimicry through the degradation of vascular endothelial cadherin (VE-cadherin or cadherin-5), probably leading to the release of β-catenin in the cytoplasm and nucleus." (PMID 39202425, 2024). "The expression can also allow the melanoma cells to progress and migrate to other parts of the body by binding to vascular endothelium and undergoing transepithelial migration via E-selectin, and through altering the tight junction modulator VE-cadherin (CDH5)." (PMID 34439879, 2021). "Indeed, melanoma sphere assays also revealed a deficient commitment to form spheres in the absence of ADAMTS1, directly correlating with stemness markers and, remarkably, also with CDH5." (PMID 32230715, 2020). "Because Flrt2 acts primarily as a repulsive ligand for the Unc5b receptor, we injected endothelial cell–specific Unc5b-knockout mice (Cdh5-BAC-CreERT2Unc5bfl/fl; referred to hereafter as Unc5biΔEC mice) with B16 melanoma cells." (PMID 35104247, 2022). "Previously, we described the capacity of CDH17 and CDH5 (VE‐cadherin) to promote liver and lung metastasis, by interacting with α2β1 integrin via their internal RGD motif, in different tumors (colorectal, melanoma, and breast cancer)." (PMID 33715292, 2021).
melanoma (continued). "RT-PCR documented mRNA expression in all the melanoma cell lines analyzed (WM115, WM266.4, and the positive controls M10 and M14) for VEGF, FGF2, CDH2, CDH5, MMP-2, MMP-9, and the two isoforms of MCAM/MUC18." (PMID 28107182, 2017). "Therefore, according to the similar behavior of CDH5 and NANOG in our melanoma culture model, we evaluated their relationship in tumor sections." (PMID 32230715, 2020).
breast carcinoma (77 papers, 2006 to 2025). "Many studies had reported that CDH5 expression is associated with multiple tumors, such as gastric cancer and breast cancer, but the relationship between CDH5 and LUAD is still to be determined." (PMID 33062704, 2020). "As would be expected, the majority of the breast cancer patients studied here were treated with the hormone therapy Tamoxifen, and this was associated with an increased CDH5:HPA ratio." (PMID 27010749, 2016). "In our study, knockout of Stk11 in murine breast cancer cell lines resulted in significant enrichment of cytoskeleton-related gene (Bpifb4), and cell adhesion/migration-related genes (Cdh5, Plat, and Pmp22), along with enhanced tumorigenicity in vivo." (PMID 41051525, 2025). "There is evidence in prior research that Cadherin-5 (CDH5) is a potential biomarker for metastasis of breast cancer." (PMID 34991439, 2022). "We also investigated the possible relationship between TACC3, Notch4, and CDH5 in the proliferation of breast cancer cells." (PMID 34149795, 2021). "We have investigated E0771.lmb breast carcinoma metastasis in mice with conditional deletion of the Shb gene using the Cdh5-CreERt2 transgene, resulting in inactivation of the Shb-gene in EC and some hematopoietic cell populations." (PMID 34768912, 2021). "To verify the correlation between TACC3 and Notch4 and CDH5, we examined the RNA-seq data (N = 4,712) of breast cancer cohort in the TCGA database by using bc-GenExMinerv 4.4." (PMID 34149795, 2021). "Recent studies showed that CDH5 levels and CDH5 glycosylation are biomarkers for metastatic breast cancer and TRIB1 plays a critical role in cell cycle and survival via NF-κB signaling." (PMID 32256525, 2020). "Work by Xiaoman indicates that CDH5 can suppress the metastasis of breast cancer owing to the ability of its 3’-UTR serve as a ceRNA for STARD13." (PMID 33075110, 2020). "VE-cadherin, also known as cadherin-5, is an adhesion molecule uniquely expressed in endothelial cells that has been used to assess microvessels and angiogenesis in human breast cancer." (PMID 30483898, 2019). "Univariate analysis revealed that CDH5:HPA ratios correlated with several prognostic indicators for breast cancer metastasis." (PMID 27010749, 2016). "In this study we aimed to further validate the utility of CDH5 as a biomarker for breast cancer progression." (PMID 27010749, 2016). "An ELISA-based methodology was developed to enable the CDH5 protein levels to be measured in the serum of breast cancer patients alongside assessment of CDH5 glycosylation status using HPA as the glycan recognition molecule." (PMID 27010749, 2016). "Comparable results to those obtained previously were observed, further strengthening the evidence for CDH5 as a biomarker of breast cancer metastasis and demonstrating the importance of assessing both the protein level and glycosylation status." (PMID 27010749, 2016). "The CDH5:HPA ratio detected patients with recurrent breast cancer with ER-positive primary tumours containing vascular invasion with 82% sensitivity and 74% specificity." (PMID 27010749, 2016). "Multivariate analysis showed that the CDH5:HPA ratio best predicts breast cancer metastasis in ER-positive tumours where the tumour has invaded the vasculature." (PMID 27010749, 2016). "Post-menopausal ER- and PR-positive breast cancer patients with metastatic disease showed significantly raised CDH5:HPA ratios compared with those who remained metastasis-free." (PMID 27010749, 2016). "Serum samples from breast cancer patients were analysed to obtain measurements of CDH5 and to determine the glycosylation status as monitored by HPA binding." (PMID 27010749, 2016). "Levels of CDH5 were determined in breast cancer serum samples by interpolation from standard curves showing intra- and inter-assay coefficients of variation of 6.8% and 15.3%, respectively." (PMID 27010749, 2016).
breast carcinoma (continued). "Univariate analysis revealed that patients with recurrent breast cancer and significantly elevated CDH5:HPA ratios typically had vascular invasion, ⩾4 positive lymph nodes and a tumour >20 mm in diameter." (PMID 27010749, 2016). "In this study we aimed to further determine the utility of CDH5 as a biomarker for breast cancer progression by identifying clinicopathological, treatment and lifestyle factors associated with metastasis and elevated biomarker levels." (PMID 27010749, 2016). "As the majority of newly diagnosed breast cancers are ER positive it is therefore encouraging that the CDH5:HPA ratio was able to discriminate ER-positive breast cancer patients with different clinical outcomes." (PMID 27010749, 2016). "The CDH5:HPA test emerged as a novel means for detection of metastatic breast cancer in patients with ER-positive tumours that have infiltrated the vasculature." (PMID 27010749, 2016). "CDH5 is also important for tumor angiogenesis, and its expression is upregulated in the vasculature of breast carcinoma and is also identified as a metastasis marker in breast cancer." (PMID 27362942, 2016). "CDH5 has been shown to be induced in an EMT of mammary tumor cells, influencing the levels of Smad2 phosphorylation and upregulating the expression of TGF-β target genes." (PMID 24283570, 2013). "For example, SVIL is intricately involved in tumour angiogenesis in liver cancer, whilst ITGAV silencing has proven to inhibit the cell proliferation and invasion of breast cancer cell lines and CDH5 has been demonstrated as a biomarker of metastatic breast cancer." (PMID 35682908, 2022). "In breast carcinoma, CDH5 expression is upregulated and serves as a metastasis marker." (PMID 34917508, 2021). "In addition, we identified five ceRNA pairs (i.e., CDH5 with FAM212B, CDH5 with GYG2 in Module 45, TRIB1 with IL33, TRIB1 with INMT, and TRIB1 with MMRN1 in Module 110) that can be used as prognostic markers of breast cancer in BRCA-associated modules." (PMID 32256525, 2020). "Genes SIAH2, CDH5 and HS3ST2 were reported to be associated with breast cancer." (PMID 31640538, 2019). "On the other hand, it has been demonstrated that induction of CDH5 during EMT promotes breast cancer progression via TGFβ signaling indicating that in certain tumor cells, CDH5 can induce cellular responses that are in contrast to its role in cell-cell contact growth inhibition in endothelial cells." (PMID 28377727, 2017). "Similarly the CDH5:HPA ratio was elevated in the serum of HER2-positive breast cancer patients who developed recurrent disease." (PMID 27010749, 2016). "In addition, CDH5 promoted breast cancer progression via the transforming growth factor β (TGF-β) signalling pathway the same pathway that promotes cell proliferation and EMT in tumours with an invasive cellular phenotype." (PMID 27010749, 2016). "However, when considered as a categorical variable 78% of breast cancer patients with a CDH5:HPA ratio in the low category (n=36) were metastasis-free after 5 years (χ2(1, N=36)=5.56, P=0.0184)." (PMID 27010749, 2016). "Both the CDH5 protein level and the CDH5:HPA ratio were significantly increased in the sera of patients with metastatic breast cancer compared to patients that remained disease free for 5 years post breast cancer diagnosis." (PMID 27010749, 2016). "Notch4 and CDH5 are two important genes involved in EMT and the aggressive phenotype of breast cancer." (PMID 34149795, 2021). "By analyzing the mRNA microarrays from TCGA, we determined that LATS1/2 level was positively correlated with STARD13, CDH5, HOXD1, and HOXD10 levels in breast cancer tissues, respectively." (PMID 29848346, 2018). "Despite multiple relationships, our study provide solid evidences to outline the novel roles of STARD13-, CDH5-, HOXD1-, and HOXD10-3’UTRs in modulating breast cancer metastasis via competing for miR-9, miR-10b and miR-125b in vitro and in vivo." (PMID 26985770, 2016).